TGFB1 (transforming growth factor beta 1)
Diseases named in the same sentence as TGFB1 in open-access papers (continued):
Sharing a sentence is not in itself a finding about the gene and the disease.
pulmonary fibrosis (continued). "Interestingly, the IL1β pathway has been associated with the development of lung fibrosis, stimulating collagen synthesis and the proliferation of fibroblasts and promoting the expression of the pro-fibrosis marker TGFβ1." (PMID 38542124, 2024). "Furthermore, higher levels of TGFB1 were reported to be associated with pulmonary fibrosis, including COVID-19 patients." (PMID 37389217, 2023). "TAC has also been associated with other actions in vitro, such as promoting the expression of transforming growth factor-beta 1 (TGF-β1), which could underly the nephrotoxicity and pulmonary fibrosis associated with this drug." (PMID 36676680, 2022). "Additionally, we aimed to examine the possible association of SIRT1 with a known mediator of lung fibrosis, TGFβ1." (PMID 36457607, 2022). "In addition, SMOC2 also participates in pulmonary fibrosis and hepatic steatosis caused by a high-fat diet targeting TGFβ1 pathways." (PMID 36935650, 2022). "Different allelic variants of the TGFβ1 gene have been identified in patients with pulmonary fibrosis and asthma, and may cause chronic obstructive pulmonary disease (COPD) in interaction with environmental factors (cigarette smoke)." (PMID 34945117, 2021). "Adrenergic-stimulated histological lung fibrosis is associated with a remarkable increase in TGFβ1, collagen I, MMP-2 and TIMP-2 mRNA expression, suggesting a link between adrenergic stimulation, the up-regulation of ECM molecules and the promotion of fibrotic processes." (PMID 34071777, 2021). "Further, inhibiting both TGFβ2 and TGFβ3 while sparing TGFβ1 could alleviate lung fibrosis while avoiding toxicity concerns associated with pan-TGFβ blockade." (PMID 34785671, 2021). "Interestingly, CM414 also antagonized the upregulation of phosphatidylinositol-3 kinase (PI3K) catalytic subunit mediated by TGFβ1, a response that has been linked to the activation of lung fibroblasts and the development of pulmonary fibrosis." (PMID 33322158, 2020). "Dysregulated or aberrant TGFβ1 signaling is implicated in numerous pathological conditions including cancer, pulmonary hypertension, and a wide variety of organ-specific fibrotic diseases, including renal and idiopathic pulmonary fibrosis (IPF)." (PMID 21625455, 2011). "Furthermore, the loss of AGER in the pulmonary fibrosis was induced by TGFB1 and TNF-alpha." (PMID 35185901, 2022). "To demonstrate whether the transcriptional downregulation of PINK1 by TGFβ1 in normal human lung fibroblasts is recapitulated in animal models of pulmonary fibrosis, we exposed mice to 3 × 108 PFU of replication-deficient adenovirus encoding either GFP (AdGFP) or active TGFβ1 (AdTGFβ1)." (PMID 26059457, 2015). "Specifically, AOP241 - Latent TGFβ1 Activation Leading to Pulmonary Fibrosis, characterises lung fibrosis as an AO triggered by nanotubes as a stressor involving the TGFβ signalling pathway." (PMID 41545907, 2026). "In idiopathic pulmonary fibrosis-derived fibroblasts, Ca2+activated KCa3.1 potassium channels promoted TGFβ1-dependent profibrotic responses." (PMID 41556665, 2026). "Administration of a TGFβ1-expressing plasmid increased Tregs producing TGFβ1 and IL-10, ameliorating pulmonary fibrosis in mice." (PMID 40247299, 2025). "Background/Objectives: Transforming Growth Factor-beta (TGFβ1) plays a core role in the process of pulmonary fibrosis (PF)." (PMID 40006524, 2025). "At 21 d.p.i., deletion of both Yap and Taz in myofibroblasts strongly attenuated lung fibrosis and suppressed the expression of key myofibroblast activation and profibrotic genes, including Acta2, Col1a1, Postn, Fn1, Col3a1, and Tgfb1." (PMID 40454481, 2025). "Regulation of fibrotic foci formation through TNF/NF-κB and TGFβ1 signaling pathways by SC offers a new therapeutic approach for treating pulmonary fibrosis." (PMID 41361355, 2025).
pulmonary fibrosis (continued). "We analyzed RNA-seq data from a bleomycin-induced pulmonary fibrosis mouse model and identified a network of oxidative stress-related fibrosis genes centered on Tgfb1." (PMID 40978478, 2025). "TGFβ1 has been shown to promote tissue fibrosis and chronic inflammation, with the TGFβ/Smad signaling pathway being a key driver of pulmonary fibrosis in ICI-induced pneumonia." (PMID 40722787, 2025). "A bleomycin (BLM)-induced pulmonary fibrosis mouse model and Transforming Growth Factor Beta 1 (TGF-β1)-induced EMT models in A549 and BEAS-2B cells were employed." (PMID 40808692, 2025). "In mice treated with BLM, atRA attenuated the upregulation of IL-17A, IL-10, IL-6, EphA2, EphriA1, PI3K 110γ, Akt, IL-6, TNF-α, and TGFβ1, which reduced pulmonary fibrosis and significantly alleviated lung fibrosis." (PMID 40508111, 2025). "Chronic inflammation and pulmonary fibrosis after COVID-19 are tied to dysregulation of networks 9 and 7c, leading to excessive TGFβ1 signaling and decreased mir-132." (PMID 41437993, 2025). "For example, oxidative stress/TGFB1 activates intrapulmonary myofibroblasts in idiopathic pulmonary fibrosis, and bleomycin recruits bone marrow-derived fibrocytes in bleomycin-induced pulmonary fibrosis." (PMID 39748675, 2025). "It is this gap that our study seeks to address, specifically investigating the role and impact of TMEM176B on the TGFβ1-SMAD signaling pathway in the context of pulmonary fibrosis." (PMID 39170226, 2024). "Transforming growth factor-beta 1 (TGFβ1) is a potent multifunctional cytokine that is known to play a central role in the pathogenesis of fibrotic diseases including pulmonary fibrosis." (PMID 39170226, 2024). "To investigate the functional role of TMEM176B, we induced pulmonary fibrosis in mice using bleomycin, TGFβ1, and silica, which consistently resulted in a marked decrease in TMEM176B expression." (PMID 39170226, 2024). "Mechanistically, TMEM176B appears to mitigate pulmonary fibrosis by inhibiting the TGFβ1-SMAD signaling pathway, which is a critical mediator of fibroblast proliferation and differentiation and promotes extracellular matrix production." (PMID 39170226, 2024). "The mechanism by which TMEM176B mitigates pulmonary fibrosis appears to be related to the inhibition of the TGFβ1-SMAD signaling pathway." (PMID 39170226, 2024). "To elucidate the mechanism of cilengitide in this lung fibrosis model, we assessed the TGFβ1 concentration in mouse serum samples." (PMID 38239077, 2024). "Collectively, these data indicated that CFH and FHL2 are involved in the pulmonary fibrosis and activation of fibroblasts induced by bleomycin and TGFβ1, respectively." (PMID 38784225, 2024). "Among these, TGFα and TGFβ1 have been shown to function as pivotal profibrotic growth factors with evidence of their involvement in fibroblast activation and the development of pulmonary fibrosis in both human subjects and animal models." (PMID 38646784, 2024). "Recent studies have demonstrated that knocking out αv in myofibroblasts effectively reduces TGFβ1 activation and prevents fibrosis in the liver, kidney and heart and bleomycin‐induced pulmonary fibrosis in murine models." (PMID 38239077, 2024). "In pulmonary fibrosis, the TGFβ1-SMAD pathway is often overactivated, leading to enhanced fibroblast proliferation, myofibroblast differentiation, and ECM production, which collectively contribute to the fibrotic changes observed in the disease." (PMID 39170226, 2024). "Elevated levels of TGFB1 were found in the lungs of STZ-induced diabetic rats and were associated with pulmonary fibrosis." (PMID 38900131, 2024). "To characterize the kinetic effects of 2 U/kg i.t. bleomycin on various biochemical markers of lung fibrosis, we measured the concentrations of TGFβ1, IL6, TNFα, IL1β, CINC1, WISP1, VEGF, and TIMP1 in BALF at days 3, 7, and 14 following instillation." (PMID 38534359, 2024).
pulmonary fibrosis (continued). "TGFβ1 is elevated in bronchoalveolar lavage fluid (BALF) of patients with IPF, and mouse pulmonary fibrosis (PF) models and genetic polymorphisms in tgfb are associated with IPF disease progression." (PMID 37643008, 2023). "Inhibition of mTORC1 with rapamycin has been used as an effective treatment for TGF‐α‐induced pulmonary fibrosis caused by chronic inflammation, but is ineffective at treating TGFβ1‐induced pulmonary fibrosis." (PMID 36798047, 2023). "CCRL2 was downregulated in IPF samples, bleomycin-induced pulmonary fibrosis, and TGFβ1-induced fibroblast." (PMID 37122736, 2023). "Other drugs, such as pirfenidone, which targets TGFβ1, and lademirsen, which targets miR21, and pulmonary fibrosis drugs, such as nintedanib, PRM-151, epigallocatechin gallate, ziritaxestat, trametinib (MEK inhibitor), and anti–IL-11 antibody, are under study." (PMID 37831322, 2023). "Quantitative measurements proved that the increase in cell stiffness is accompanied by cytoskeleton rearrangement in TGFβ1-induced pulmonary fibrosis." (PMID 38147026, 2023). "First, lung tissue specimens from patients with IPF were not available to validate the analysis, despite using a bleomycin-induced lung fibrosis model and a TGFβ1-induced cell model." (PMID 37122736, 2023). "There is a strong connection between the classic driver of fibrosis, TGFβ1 and an increase in these metabolic processes in pulmonary fibrosis, liver fibrosis, skin fibrosis, and systemic sclerosis." (PMID 37476157, 2023). "A6 was found to have effective anti-fibrotic activity both in vitro on TGFβ1-stimulated lung fibroblasts and in vivo on bleomycin-induced lung fibrosis in mice." (PMID 37569677, 2023). "In chronic vitamin D deficient mice, triggering of the renin-angiotensin system (RAS) led to activation of TGFβ1 and pulmonary fibrosis." (PMID 36835058, 2023). "Understanding the TGFβ1 signaling mechanism is important in lung fibrosis, which begins with ECM tension and subsequently extensive ECM deposition." (PMID 36767821, 2023). "Taken together, we uncover a determinate role of the TGFβ1-Rcn3-TGFBR1 loop in the pathogenesis of pulmonary fibrosis, as well as introduce a novel regulating mechanism of TGFβ1 signalling." (PMID 37710230, 2023). "By affecting oxidative stress, TGFβ1 is also a prominent factor in the development of idiopathic pulmonary fibrosis." (PMID 38132468, 2023). "Previous studies have indicated that eupatilin exerts an anti-fibrogenic effect on TGFβ1-induced endometrial fibrosis and bleomycin-mediated lung fibrosis." (PMID 36983006, 2023). "Human TGFβ1 transgenic mice with a CT score-matched lung fibrosis received BLM or SAL through osmotic mini-pumps and then treated with anticorisin mAtb or irrelevant IgG three times a week, and the mouse survival was followed." (PMID 35322016, 2022). "Among them, transforming growth factor-beta 1 (TGF-β1) is the most studied profibrotic cytokine that is involved in the development of pulmonary fibrosis." (PMID 36267283, 2022). "The E3 region of endostatin reduces lung fibrosis induced by bleomycin and skin fibrosis induced by bleomycin and TGFβ1 in vivo." (PMID 36359382, 2022). "We also provide in vivo and in vitro evidence that NecroX-5 attenuated pulmonary fibrosis and the TGFβ1/Smad2/3-mediated EMT process." (PMID 35596212, 2022). "We next evaluated the effects of TGFβ1 siRNA-loaded MANPs on bleomycin-induced lung fibrosis for up to 15 d." (PMID 35377803, 2022). "Next, we validated END55 in a second mouse model of pulmonary fibrosis involving doxycycline-inducible expression of bioactive human TGFβ1 in lung tissues." (PMID 36359382, 2022). "We show that DNMT3B deficiency promotes alternative macrophage polarization induced by IL4 and TGFB1 in vitro and also enhances profibrotic macrophage polarization in the alveolar space during pulmonary fibrosis in vivo." (PMID 35725453, 2022).
pulmonary fibrosis (continued). "Next to test the effects TGFβ1-siRNA-MANP in a model of established lung fibrosis, we assessed a different treatment regime." (PMID 35377803, 2022). "Significant reductions were also seen in TGFβ1 expression in Mo-AMs obtained after treatment with TGFβ1-siRNA-MANPs in the 7-d and 15-d lung fibrosis mice." (PMID 35377803, 2022). "Tissues from IPF patients and from transforming growth factor β1 (TGFβ1) transgenic (TG) mice with lung fibrosis enrich for halophilic bacteria." (PMID 35254127, 2022). "TGFb1 overproduction has been recognized as the most relevant factor related to the progression of pulmonary fibrosis." (PMID 35172279, 2022). "This last fact supports the role of TGFβ1/Smad3 signaling pathway and its possible importance as a therapeutic target for the treatment of lung fibrosis." (PMID 35743055, 2022). "Only one study, on idiopathic pulmonary fibrosis, has shown that fructose can indirectly promote fibrosis through the stimulation of latent TGFβ1 in human epithelial cells." (PMID 36235741, 2022). "TGFB1 is an important cytokine driving pulmonary fibrosis and mostly produced by macrophages during fibrosis." (PMID 35725453, 2022). "The TGFβ1 TG mice with lung fibrosis and BLM-induced AE treated with the anticorisin mAtb showed significantly longer survival than those treated with the control IgG." (PMID 35322016, 2022). "PTX2 reduced the differentiation of monocytes towards M2 macrophages and fibrocytes and inhibited lung fibrosis in preclinical models of TGFβ1‐ and bleomycin‐induced fibrosis." (PMID 36336784, 2022). "We found that the carboxyl-terminal region (E3) abolishes TGFβ1-induced fibrosis in human skin explants and reduces skin and lung fibrosis in murine models of fibrosis." (PMID 36359382, 2022). "In stark contrast to previously used Adenovirus-based models that only induce transient TGFβ1 expression due to antiviral immune responses, the AAV-TGFβ model leads to persistent expression of TGFβ and consequently to a progressive worsening of lung fibrosis." (PMID 35842487, 2022). "This oxidase family is stimulated by transforming growth factor beta (TGFβ1), which increases superoxide synthesis and favors oxidative stress, promoting lung fibrosis." (PMID 35743055, 2022). "In conclusion, AOBEE promoted KLF4 degradation leading to the attenuation of pulmonary fibrosis by inhibiting TGFβ1–smad/p38MAPK–lnc865/lnc556–miR-29b-2-5p–STAT3 signal pathway." (PMID 33929970, 2021). "Other research reported that the interaction between TGFβ1 and different complement components exacerbated epithelial damage in pulmonary fibrosis." (PMID 34433493, 2021). "As the TGFβ1 and, in some cases, mTORC1 pathways are crucial to other fibrotic diseases, such as pulmonary fibrosis and chronic renal fibrosis, it will be vital to evaluate the effect of PIP4k2c in these settings." (PMID 34026458, 2021). "Transforming growth factor beta (TGFβ) has been implicated in increased ECM production in pathological conditions of lung fibrosis, with TGFβ1 as the predominant TGFβ isoform expressed." (PMID 33670906, 2021). "In this case, IL-4 and IL-13, released from senescent AT2, promotes alveolar macrophage activation in lung fibrosis via the PAI-1/TGFβ1 axis." (PMID 34207528, 2021). "MitoQ combined with YFT can improve lung injury in rats with pulmonary fibrosis by reducing the secretion of proinflammatory cytokines and inhibiting TGFβ1/NOX4 and PDGF/ROCK signaling pathways." (PMID 34135982, 2021). "Animal models have demonstrated the link between TGFB1 and fibrosis, for example overexpression of TGFB1 in rat lungs induces pulmonary fibrosis." (PMID 34771552, 2021). "In the bleomycin-induced pulmonary fibrosis model, cytomegalovirus is considered to accelerate existing fibrosis according to enhancing TGFB1 activation and the expression of both phospho-SMAD2 and Vimentin." (PMID 34880861, 2021).
pulmonary fibrosis (continued). "This is in contrast to rats, where female mice challenged with endotracheal bleomycin had more severe lung fibrosis and higher tissue levels of collagen I and Tgfβ1 than male rats, and the extent of fibrosis was reduced when female rats were ovariectomized." (PMID 34830489, 2021). "The anti-fibrotic role of metformin was also examined in a bleomycin-induced lung fibrosis model, being found to inhibit TGFβ1-induced NOX4 expression." (PMID 33803835, 2021). "Extensive studies, including one based on the concept of candidate genes, have demonstrated the role of TGFβ1 in the occurrence of pulmonary fibrosis, secondary to the inflammatory response." (PMID 34945117, 2021). "In models of lung fibrosis, enhanced TGFβ1 expression precedes increased collagen and extracellular matrix deposition." (PMID 33670906, 2021). "The relevance of these findings is demonstrated within the context of TGFB1 signaling and idiopathic pulmonary fibrosis, suggesting therapies against this lethal disease." (PMID 33594057, 2021). "In order to determine the changes of TGFβ1/NOX4 and PDGF/ROCK signal pathway in idiopathic pulmonary fibrosis after Yifei decoction combined with MitoQ intervention, we detected the expression levels of TGFβ1, NOX4, PDGFR-β, and ROCK1." (PMID 34135982, 2021). "This study compared the therapeutic efficacy between the oral and intranasal PFD administration in mice with human TGFβ1-driven lung fibrosis." (PMID 33390975, 2020). "The development of pulmonary fibrosis in our mouse overexpressing TGFβ1 is a proof-of-concept for the critical role of this cytokine in tissue fibrosis." (PMID 32210242, 2020). "Myofibroblasts induced by TGFβ1 and other factors are key players in the pathogenesis of lung fibrosis and tumor." (PMID 32943605, 2020). "A final example is found in idiopathic pulmonary fibrosis development, where transforming growth factor beta 1 (TGFB1) mediates the down-regulation of NUDT21 via induction of miR-203 resulting in APA shortening." (PMID 32560344, 2020). "In brief, the results of this study showed for the first time that PFD is a potent inhibitor of human TGFβ1-driven lung fibrosis in vivo and that intrapulmonary delivery of low doses of PFD evokes therapeutic response equivalent to high doses of oral PFD." (PMID 33390975, 2020). "The development of severe pulmonary fibrosis resembling the human disease in mice with lung-specific overexpression of human TGFβ1 is the proof-of-concept of the pivotal role of TGFβ1 in pulmonary fibrosis." (PMID 33390975, 2020). "More specifically, mice with a conditional deletion of Tgfb1 in macrophages were protected from pulmonary fibrosis." (PMID 33141839, 2020). "AGF and TGFB1 mRNAs were increased in the patients with both forms of lung fibrosis compared to controls, but CTGF mRNA was decreased in IPF patients compared to other groups." (PMID 32664949, 2020). "To summarize, the inflammation is regarded as the initial phase of pulmonary fibrosis that activates the next phase in which TGFβ1 is secreted." (PMID 33101446, 2020). "The TGFB1 gene product is a secreted protein with numerous functions, including roles in lung development and disease; TGFB1 appears to be the predominant isoform involved in pulmonary fibrosis." (PMID 30828372, 2019). "MEVs suppress TGFβ1-induced myofibroblastic differentiation of normal and idiopathic pulmonary fibrosis (IPF) lung fibroblasts, thus mitigating tissue fibrotic response." (PMID 31412612, 2019). "We have recently demonstrated an interconversion between lipogenic and myogenic fibroblastic phenotypes in lung fibrosis, a process that is governed by TGFβ1 and PPARγ signaling pathways." (PMID 31278260, 2019). "In this study, the in vitro effects of raltegravir (RAV) on transforming growth factor beta 1 (TGF-β1)-induced pulmonary fibrosis on L929 mouse fibroblasts were investigated." (PMID 31481891, 2019).